CD59 (CD59 molecule (CD59 blood group))
Diseases named in the same sentence as CD59 in open-access papers (continued):
Sharing a sentence is not in itself a finding about the gene and the disease.
tumor (continued). "Previous efforts also indicated that the protein contents of Fas and anti-apoptotic Bcl2 were elevated and reduced respectively in H157 tumours expressing siRNA specific to the complement inhibiting protein CD59, although whether the changes involved epigenetic regulation were unknown." (PMID 26891293, 2016). "Although the MAC can directly lyse tumor cells by disrupting membrane integrity, CRC cells evade complement-mediated cytotoxicity by upregulating CRPs such as CD55, CD46, and CD59 via STAT3/STAT6/p38 MAPK signaling." (PMID 41031883, 2025). "Tumor cells often overexpress membrane complement regulatory proteins (mCRPs) such as CD55, CD46, and CD59, which inhibit complement activation and protect against complement-mediated cytotoxicity." (PMID 40806542, 2025). "For instance, CD59 prevents the formation of the membrane attack complex (MAC), thereby shielding tumor cells from lysis." (PMID 40806542, 2025). "In contrast, CD59 is significantly upregulated in colorectal cancer (CRC) tissues, potentially facilitating tumor evasion of complement-mediated lysis." (PMID 41031883, 2025). "Neutralizing antibody treatment against CD55 (decay accelerating factor) and CD59 results in complement and CD8 + T cell activation and inhibits tumor growth." (PMID 39747856, 2025). "Tumor cells express membrane-bound complement regulatory proteins (mCRP; CD35, CD46, CD55, and CD59) that normal cells use to prevent excessive activation of complement cascades in the early stages of an immune response." (PMID 39125875, 2024). "Specifically, it was possible to identify inhibition interactions in the targets mAb CD73 and CD59, and in the mutant K-RAS oncogene, by interrupting processes related to carcinogenesis and tumor formation." (PMID 39598781, 2024). "The scRNA-seq analysis revealed that candidate Siglec-9 ligands CD59, CD47, and LGAL3BP were expressed in tumor cells in metastatic tumor tissues derived from patients with CRPC." (PMID 39436703, 2024). "Clinically significant cancers with high CD59 expression were further examined for immune subtype analysis using the TISIDB database, a central resource for studying tumor-immune system interactions." (PMID 39518137, 2024). "On the other hand, the part of CDC in killing tumor cells in vivo is less clear, particularly for solid tumors, in part because tumor cells themselves express membrane-bound complement regulators (CD46, CD55, and CD59)." (PMID 38085594, 2024). "The high expression of CD59 on cancer cells facilities their evasion from CDC, leading to tumor progression." (PMID 39518137, 2024). "The ability of CD59 to inhibit MAC formation and downregulate CD4+ T cells plays an important role in the suppression of tumor immune environments." (PMID 39518137, 2024). "Other regulators of tumor biology, including PTPRS, CSPG4, SPRED1, CD59, and PROCR, were all downregulated upon CBX3 knockdown." (PMID 39545414, 2024). "In the primary tumor, APLP2, BNIP3L, CD59 and DKK3 were highly expressed in 29.7% (n = 38), 64.9% (n = 83), 92.2% (n = 118) and 80.5% (n = 103), respectively." (PMID 35796776, 2023). "Analysis of complement activity within treated tumors revealed that CD55/CD59 double-knockdown resulted in a further increase of C3b deposition, MAC formation, and direct tumor lysis after T+P therapy." (PMID 35167491, 2022). "Tsao showed that survival in HER2+ breast cancer is inversely related to tumor levels of CD55 and CD59." (PMID 36291900, 2022). "Analysis of complement system activation on tumor tissues showed the co-expression of PTX3 with C1q, C3aR, C5R1, and CD59." (PMID 35651807, 2022). "Taken together, our data indicate that mCRPs, such as CD46, CD55, or CD59, are increased during CTL-mediated immunoediting, and they, especially CD59, contribute to CDC resistance of immune-edited tumor cells." (PMID 35606403, 2022).
tumor (continued). "LY6D, LY6E, PLAUR, PSCA, CD59 and LYPD3 mRNA expression was significantly increased in the PDAC tumor tissues than normal adjacent tissues (p < 0.01)." (PMID 33613843, 2021). "A major concern is the presence on tumor cells of inhibitory membrane-bound complement regulatory proteins (mCRPs) such as CD46, CD55, and CD59, which enable cancer cells to evade complement attack." (PMID 35052426, 2021). "Second, the MACC-induced CD59 clusters activate the extracellular signal-regulated kinase (ERK) signaling pathway, thus enhancing tumor cell proliferation." (PMID 33053147, 2020). "The burden of functional connection of CD59 with CLU may enhance its value due to association with cell lysis resistance and, consequently, the encouraging of tumor growth, but an expression of different CD antigens and their implication in tumor expansion remains uncertain." (PMID 32023884, 2020). "First, CD59 renders autologous carcinoma cells insensitive to the MACC action, providing tumor cells with a key strategy to evade the immune system." (PMID 33053147, 2020). "As observed for tumor cells, exosomes display CD55 and CD59, conferring resistance against complement-mediated lysis, and potentially regulating the exosome-mediated cross-talk associated with the metastatic program." (PMID 31001273, 2019). "In primary tumor sections, CD55 and/or CD59 were found in the stroma of breast, colorectal, lung, renal, and cervical carcinomas." (PMID 31024572, 2019). "Mechanisms of primary and/or acquired resistance include tumor-related factors, such as reduced cell surface expression levels of the target antigen and high levels of complement inhibitors (CD55 and CD59)." (PMID 30294326, 2018). "We excluded markers that are known to be ubiquitously expressed on all nucleated cells (e.g. HLA) or on tumour cells (e.g. CD47) and focused our attention on five markers (CD57, CD59, CD81, CD164 and CD98) for further interrogation." (PMID 27590276, 2016). "In this study, we have found that the complement system is unexpectedly activated in latently KSHV-infected endothelial cells and in KS tumor cells wherein KSHV downregulates the expression of CD55 and CD59 complement regulatory proteins." (PMID 25254972, 2014). "NPA cells expressed all the three proteins, with a greater expression of CD59 and CD55 than CD46 proteins, suggesting that NPA tumour cells were obviously protected against CDC." (PMID 20145622, 2010). "In NT2-N neuronal cell lines, relatively high expression levels of CD46, CD59 and CD55 are found, however, NT2-N are differentiated from NTERA-2 tumour cells (malignant pluripotent embryonal carcinoma) and tumours are known to overexpress these CReg proteins." (PMID 19721814, 2009). "These tumour cells are immunohistochemically positive for S-100 protein (supporting the neural origin of granular cell tumour), as well as for neuron-specific enolase, CD68, calretinin, CD57, inhibin, TFE3, SOX, CD59, PGP9.5, and vimentin." (PMID 40256332, 2025). "CD59 is expressed in cancer cells in localized, HSPC, and CRPC tumor tissues." (PMID 39436703, 2024). "Intriguingly, the EVs secreted by invasive tumoroids (3D d10‐d14) contained several unique proteins promoting tumour growth and invasion, for example, SLC4A7, SLC12A2, FABP5, PRDX1, CD59 and CD73, showing that specific oncogenic signals are loaded in EVs upon invasion." (PMID 38938900, 2023). "Studies have found that tumor cells can block complement activation cascades and inhibit MAC formation via membrane complement regulatory proteins (mCRPs), such as CD46, CD55, and CD59." (PMID 37907575, 2023). "The alignment of our experimental findings with clinical data provides valuable insights into the potential clinical relevance of CD59 and CD73 in cancer, suggesting that these proteins could potentially serve as biomarkers of tumour progression." (PMID 38938900, 2023).
tumor (continued). "This phenomenon could be due to the expression of several different complement-regulatory proteins (CRPs) by tumor cells, such as CD46, CD55, and CD59, which inhibit complement activation and confer resistance of tumor cells to killing mediated by CDC." (PMID 35804808, 2022). "Importantly, tumor-infiltrating cDC1s showed significantly higher surface levels of MHC-I, as well as the RIDD marker CD59 in G9668-treated mice as compared with controls." (PMID 35446348, 2022). "Assessment of tumor signatures, such as CD20/CD59 ratio, can be advantageous to predict CDC efficiency of RTX in vivo and may help to develop rational mAbs to raise response rates in patients." (PMID 35725455, 2022). "Collectively, our results revealed a possible mechanism through which selection imposed by T-cell based immunotherapy triggered complement-resistant phenotypes in the tumor microenvironment (TME), by establishing a firm molecular link between NANOG and CD59 in immune-edited tumor cells." (PMID 35606403, 2022). "The ICT-CMC-CD59sp microspheres constructed in this experiment can bind CD59sp specifically to the tumor cell CD59 to guide the drug to the surface of oral squamous cancer cells, intake Epanin inside the cells, activate the complement to form MAC and lyse OSCC tumor cells." (PMID 35387305, 2022). "The pretreatment expression of CD38 was correlated with a better outcome to daratumumab, while lack of response and tumor progression was associated with expression of both CD55 and CD59." (PMID 34299097, 2021). "Considering that the expression of CD20 is prerequisite for rituximab anti-tumor activity, the appropriate strategy for overcoming resistance should down-regulate the expression of only inducible CD59 but not CD20." (PMID 34956875, 2021). "Although heterogeneous relative to tumor type, complement proteins expressed by malignant cells are variable; in general, tumor cells express low C8 and C9 but highly express C3 and the regulators factor H, factor I and especially the membrane regulators CD46, CD55 and CD59." (PMID 33147799, 2020). "The role of complement activation and membrane inhibitors expressed by tumor cells, most notably CD55 and CD59, has also been quite extensively studied, but how much these affect the resistance of tumors in vivo to IgG1 therapeutic mAbs still remains incompletely understood." (PMID 33126570, 2020). "NSE, GRP78, CD55 and CD59 sometimes increased, but for each patient the response of the non-cancerous prostate sample was weaker than that of the tumour sample." (PMID 30820548, 2019). "Apart from CD59, CD46, and CD55 could also enable tumor cells to evade CDC and function as complement regulators." (PMID 31685825, 2019). "Nevertheless, these tumours showed induction of CK8, CK18, GRP78, CD55, CD59 and CD63 mRNAs." (PMID 30820548, 2019). "Anti-CD38 treatment may also generate resistance and induce tumor immune escape, through the up-regulation of two complement inhibitor proteins, CD55 and CD59 on MM cells." (PMID 30546360, 2018). "Interestingly, in some MM tumors there are coexisting subpopulations of tumor cells with markedly different levels of CD55 and CD59 expression." (PMID 30294326, 2018). "There was no statistical correlation between CD59 expression levels and age, gender, or tumor stage of the patients." (PMID 30166523, 2018). "Lack of post-transcriptional regulation of CD59 due to miR-10a-5p downregulation in eBL patients would enhance tumor cell survival and possibly increase relapse rates." (PMID 28400759, 2017). "CD59 and CD46, also highly expressed in IH, prevent complement-mediated tumor cell lysis." (PMID 27786256, 2016). "In agreement with the cell culture results, we observed weak or close to no expression of CD55 and CD59 on the typical spindle tumor cells in KS tumors." (PMID 25254972, 2014).
tumor (continued). "Interestingly, our data on exosomal protein profiles from treated Caco-2 showed an enrichment of upregulated proteins involved in tumor etiopathogenesis, including CRC (CD59, CRP, CTSD, HMMR, LY6K, TRIM22), and in cell cycle control (BRAF, CDC2, ERBB2)." (PMID 25594007, 2014). "Indeed, we have found that complement regulatory proteins CD55 and CD59 are significantly downregulated in latently KSHV-infected endothelial cells and in KS spindle tumor cells." (PMID 25254972, 2014). "As CD59 can interact with CD2 on T cells, there may even be a selective pressure against CD59 expression on tumour cells to avoid interaction with T cells." (PMID 15655555, 2005). "Ofcourse, the tumor rejection antigens and stage specific antigens have been well characterized on human embryos, but there are many others such as the TEC antigens (TEC1- TEC4), LeX, LeY, CD46, CD55, and CD59." (PMID 16033656, 2005). "By contrast, focal expression or even complete lack of CD59 was more often found in poorly differentiated tumours (P = 0.021)." (PMID 7692919, 1993). "Targeting CD59 on both immune and tumor cells could potentially offer a novel therapeutic strategy for these cancers." (PMID 39518137, 2024). "Since CD59 is expressed in all cells, including both tumor and immune cells, solely silencing or overexpressing it in tumor cells may not yield predictive results." (PMID 39518137, 2024). "CD59 could inhibit complement and CD8+ T cell activation, leading to immune evasion and immune checkpoint blockade, which was also overexpressed in HNSCC and regulated tumor metastasis and prognosis." (PMID 38157249, 2023). "In the present study, the three markers from the fibrosome with the highest reported predictive values (APLP2, BNIP3L, CD59) and an additional well-known fibrosis marker (DKK3) in renal and cardiac disease were investigated on protein expression level in primary tumor samples." (PMID 35796776, 2023). "In addition to identification of plasma EV CD59 and TSPAN9 as a two-marker panel for CRC detection, the pathobiological roles of EV CD59 and TSPAN9 in the tumor microenvironment and/or chemoresistance of CRC obviously remain as intriguing issues that warrant further investigation." (PMID 36612172, 2022). "CD59 renders tumor cells resistant to CDC but does not affect ADCC." (PMID 35792784, 2022). "Interestingly, an increased CD59 expression has been reported in several neoplasia, although no information is available on the level of CD59 expression within neoplastic renal tissue." (PMID 32345771, 2020). "Previous studies had shown that CD59 was highly expressed in a variety of solid tumors and cells, acting as a complement regulatory protein that prevented MAC formation by binding to C8 or C9, thereby protecting tumor cells from complement-mediated cytolysis and evading immune detection." (PMID 30636930, 2019). "The expression of CD55 and CD59 are related to herceptin-induced complement-dependent cytotoxicity (CDC), and also promote suppressed anti-tumor effectiveness of herceptin, suggesting that CD55 and CD59 may be useful markers for predicting the clinical response to Herceptin therapy." (PMID 22634835, 2012). "The observation that AF from patients with other large-sized gynaecological tumours of different histological types (both malignant and benign) also contained high levels of CD59 suggests that the release of CD59 from cells is related to tumour mass rather than to the malignancy itself." (PMID 15726105, 2005). "However, complement deficiencies, the over-expression of membrane complement regulatory proteins (e.g. CD55, CD59, and CD46) and fluid phase inhibitors (e.g. CFH, CFHR5, and C4BP) in the tumor microenvironment often cause resistance and non-responsiveness to mAb treatment." (PMID 33193442, 2020).
tumor (continued). "CD59 is a glycosyl-phosphatidylinositol (GPI)-anchored cell membrane glycoprotein that inhibits complement-mediated cell lysis by preventing full assembly of the membrane attack complex (MAC) on host cells, and thus might confer immune resistance to tumor cells." (PMID 30237853, 2018). "This was carried out via a more precise method using the immunofluorescent detection of endogenous tumor cell antigens (CD29 and CD59), which unlike lipophilic membranes dyes, is not subject to lateral dye transfer." (PMID 33803526, 2021). "Analysis of complement system activation on tumor tissues showed the co-expression of PTX3 with C1q, C3aR, C5R1 and CD59, but not with C5b-9 terminal complex." (PMID 32345771, 2020).